PTPRZ1 (protein tyrosine phosphatase receptor type Z1)
Diseases named in the same sentence as PTPRZ1 in open-access papers (continued):
Sharing a sentence is not in itself a finding about the gene and the disease.
ovarian carcinoma (1 paper, 2023). A malignant neoplasm originating from the surface ovarian epithelium. "Overexpression of PTPRZ1 enhanced the sensitivity of ovarian cancer cells to cisplatin and enhanced cell apoptosis in vitro, and inhibited tumor growth and resistance to cisplatin in vivo." (PMID 37175798, 2023). "In ovarian cancer cells, PTPRZ1 negatively regulates Akt kinase activity, in line with our data on mouse Ptprz1−/− lung endothelial cells and tumors, that have increased levels of activated Akt compared to the corresponding wildtype." (PMID 37175798, 2023). "PTPRZ1 is expressed in epithelial ovarian cancer cells and enhances cell viability through the inhibition of apoptosis." (PMID 37175798, 2023). "However, PTPRZ1 mRNA levels were found to be significantly downregulated in ovarian serous cystadenocarcinoma, in line with a recent study using transcriptomic data, showing an abnormally low PTPRZ1 expression in ovarian cancer tissues and in cisplatin-resistant ovarian cancer cells." (PMID 37175798, 2023).
Parkinson disease (1 paper, 2016). A progressive degenerative disorder of the central nervous system characterized by loss of dopamine producing neurons in the substantia nigra and the presence of Lewy bodies in the substantia nigra and locus coeruleus. "Interestingly, inhibition of PTPRZ1 was suggested as a treatment for Parkinson’s disease based on delayed recovery from demyelinating lesions in a mouse model lacking PTPRZ1." (PMID 27898738, 2016).
pilocytic astrocytoma (1 paper, 2023). Pilocytic astrocytoma is a rare subtype of low-grade glioma of the central nervous system characterized by a well circumscribed, often cystic, brain tumor with a discrete mural nodule and long, hair-like projections that extend from the neoplastic astrocytes. "More recently, PTPRZ1 has been identified as a BRAF fusion partner in juvenile pilocytic astrocytomas, but information on the functional significance of this fusion protein is missing." (PMID 37175798, 2023).
squamous cell carcinoma (1 paper, 2012). A carcinoma arising from squamous epithelial cells. "To determine globally which human tumor tissues expressed PTPRZ1, we analyzed immunohistochemical (IHC) evaluations of a variety of tumors including 105 cases of adenocarcinoma (ADCA), 61 cases squamous cell carcinoma (SQCC) and 86 cases NET." (PMID 23170925, 2012).
ZIKV infection (1 paper, 2020). "Proteins previously identified to be differentially expressed during ZIKV infection include GAP43, DCX, PTPRZ1, ASNS, SLC3A2 and MKI67." (PMID 32873194, 2020).
tumor (73 papers, 2010 to 2025). "Assessing cell states, we again observed that PTPRZ1 was associated with AC-like tumor cells, but upon PTPRZ1-TCR-T cell treatment, AC-like score and AC-like tumor cell frequency were reduced significantly." (PMID 39893177, 2025). "In addition, they strongly upregulated the NSC markers Sox2, Nes, and Ptprz1, indicative of a more stem/progenitor-like state associated with tumor aggressiveness." (PMID 39285246, 2024). "The findings suggest that specific microbial species may promote or inhibit tumor progression, and a correlation between genetic mutations, such as in PTPRZ1, and microbial composition offers a novel perspective on LUAD pathogenesis." (PMID 39845316, 2024). "Indeed, PTPRZ1 showed strong staining in infiltrating cells and has been recently implicated in tumor invasion and aggressiveness." (PMID 35013227, 2022). "In concordance with transcriptomic data using GFAP to depict tumor purity, abundance of PTPRZ1+ cells correlated positively with GFAP+ cells." (PMID 39893177, 2025). "To investigate the potential role of the PTPRZ1 in tumor development, we leveraged CRISPR/Cas9 to perform knockout experiments in two distinct LUSC cell lines, H520 and HCC95, both characterized by high cellular expression of the gene." (PMID 40899632, 2025). "We also carried out the experiments using H520 cells with PTPRZ1‐KO and control, and the trend of reduced tumor growth was consistently observed in the PTPRZ1‐disrupted cells." (PMID 40899632, 2025). "Spatial transcriptomic analysis further implicates midkine (MDK) as the ligand activating PTPRZ1 in LUSC tumor tissue." (PMID 40899632, 2025). "Our data not only solidify its candidacy as a prognostic biomarker but also ignite promise for therapeutic strategies targeting PTPRZ1 to cripple tumor growth and improve clinical outcomes in LUSC patients." (PMID 40899632, 2025). "Given its established function in tumor-stromal interactions, PTPRZ1 represents a compelling target for future immunotherapeutic strategies, and in fact some groups are also employing vaccine-induced approaches in GBM30." (PMID 40517137, 2025). "This attenuation was further corroborated by a near threefold decrease in tumor weight at endpoint (P < 0.01), underscoring PTPRZ1's indispensable role in sustaining tumor mass." (PMID 40899632, 2025). "The result showed that MDK was the most significant candidate ligand interacting with PTPRZ1 among tumor cells, consistent with their co‐expression patterns." (PMID 40899632, 2025). "The single cell analysis has revealed high heterogeneity of LUSC tumor tissue and the tumor‐specific expression of the 4 master TFs as well as their target gene PTPRZ1." (PMID 40899632, 2025). "Mechanistically, PTPRZ1 mediates MDK‐induced PI3K phosphorylation that is essential for LUSC tumor growth." (PMID 40899632, 2025). "Strikingly, PTPRZ1 genetic ablation achieved potent tumor growth suppression (≈70%) in xenograft models, underscoring its therapeutic relevance in vivo." (PMID 40899632, 2025). "Strikingly, genetic ablation of PTPRZ1 unleashed a profound suppression of tumor growth, with KO tumors exhibiting a dramatic ≈70% reduction in volume compared to controls by day 37 post‐implantation (P < 0.01)." (PMID 40899632, 2025).
tumor (continued). "The epitopes are derived from four TAAs that are either over-expressed (BCAN, BIRC5, PTPRZ1) or where the epitope is over-presented (NLGNX4) in a large proportion of GBM tumours compared with most healthy tissues." (PMID 41051649, 2025). "In the context of LUAD, PTPRZ1 has been suggested to be involved in the modulation of cell adhesion and migration, which are critical steps in tumor progression and metastasis." (PMID 39845316, 2024). "Tumor-wide (100%) positivity was exhibited only for four event-case pairs (PTPRZ1-03 in tumor T2; NCAM1-01 in T24; DLL3-02 in tumors T15 and T16)." (PMID 38493204, 2024). "Further analysis was conducted using targeted RNA NGS on a fresh tumor sample, which identified a PTPRZ1-MET rearrangement." (PMID 39411129, 2024). "In summary, these findings provide a novel function of integrin α6β4 in promoting tumor invasive phenotypes through UCHL1-Hif-1α-mediated regulation of PTPRZ1." (PMID 39518121, 2024). "We uncovered that the integrin α6β4-UCHL1-Hif-1α-PTPRZ1 signaling axis promoted an invasive phenotype which is a property known to contribute to tumor progression." (PMID 39518121, 2024). "PTPRZ1 also has many substrates, including p190RhoGAP and β-catenin, which contribute to tumor progression." (PMID 39518121, 2024). "In line with the high PTPRZ1 expression in embryonic stem cells, PTPRZ1 is preferentially expressed in GBM stem cells and mediates the stimulatory effects of PTN secreted by tumor-associated macrophages on GBM growth." (PMID 37175798, 2023). "In the present review, we focus on the involvement of the transmembrane protein tyrosine phosphatase receptor zeta 1 (PTPRZ1) in cancer growth and angiogenesis and discuss its potential as a drug target or as a biomarker, depending on the tumor type." (PMID 37175798, 2023). "By assessing the elevated expression levels of gene sets corresponding to specific cell type markers, namely PTPRZ1 for tumor cells, MOBP for oligodendrocytes, and CSF1R for macrophages, we successfully classified the cells." (PMID 37662954, 2023). "This analysis suggested neoplastic tumor cell PTPRZ1 targeting by PTN, the latter largely produced by the neoplastic cells." (PMID 36966348, 2023). "We also identified the potential role of OUM1 in regulating PTP activity in the tumor microenvironment through PTPRZ1 and its effect on UM progression." (PMID 36335349, 2022). "In nude mice tumor formation experiments, it was found that silencing PTPRZ1 can inhibit the development of OSCC." (PMID 35251170, 2022). "Pleiotrophin secreted by TAMs was shown to promote PTPRZ1 signaling in GBM stem cells leading to tumor growth." (PMID 36712881, 2022). "While the frequency of cells expressing PTN increased in the transition from tumor to adjacent tissue, the frequency of cells expressing PTPRZ1 decreased in an anticorrelated fashion." (PMID 36539501, 2022). "The tumor cells included in these clusters exhibited astrocyte-like features and expressed low levels of PTPRZ1." (PMID 34692159, 2020). "They found that PTPRZ1+ cells expanded and invaded into the cerebral organoids after engraftment, and showed that PTPRZ1 plays a crucial role in tumor invasion." (PMID 32670022, 2020). "PTPRH and PTPRZ1 were expressed in a large number of NB tumor samples, mostly displaying a cytoplasmic granular staining pattern." (PMID 31837707, 2019). "We demonstrated that the expression of PTN and PTPRZ1 was upregulated by chemotherapy, and this change in expression decreased chemosensitivity by promoting tumour proliferation and inhibiting apoptosis." (PMID 30497491, 2018). "Statistical analyses of the tumour formation incidence showed that PTPRZ1+ cells initiated tumours with a higher frequency relative to the matched PTPRZ1− population." (PMID 28569747, 2017). "We revealed that the TAM-secreted PTN acts through PTPRZ1 on GSCs to promote the self-renewal and tumour propagation of GSCs." (PMID 28569747, 2017).
tumor (continued). "To interrogate the impact of the PTN–PTPRZ1 signalling on GSC-driven tumour propagation, we examined the effect of PTPRZ1 disruption on GSC tumour growth." (PMID 28569747, 2017). "The results demonstrated that co-implanted MLCs promoted GSC tumour growth, whereas the administration of anti-PTPRZ1 antibody impaired the pro-tumorigenic effect of MLCs on GSC xenografts." (PMID 28569747, 2017). "Collectively, these data demonstrate that the anti-PTPRZ1 antibody treatment is effective to inhibit GSC tumour growth." (PMID 28569747, 2017). "The bioluminescent imaging analyses demonstrated that co-implanted MLCs significantly promoted the growth of PTPRZ1+ tumours, while the supportive effect of MLCs on the PTPRZ1− tumours was less significant." (PMID 28569747, 2017). "GSCs (T0912) expressing luciferase were incubated with the anti-PTPRZ1 antibody or control IgG and then implanted into mouse brains followed by intravenous administration of anti-PTPRZ1 antibody or the isotype IgG throughout the period of tumour growth." (PMID 28569747, 2017). "Bioluminescence analyses demonstrated that the anti-PTPRZ1 antibody treatment markedly retarded GSC tumour growth." (PMID 28569747, 2017). "Collectively, these data demonstrate that disruption of PTPRZ1 effectively attenuates the tumour-propagating capacity of GSCs." (PMID 28569747, 2017). "To address the question if Rptpζ would act as a tumor suppressor in human OS we first analyzed, if PTPRZ1 is differentially expressed during differentiation of human osteoblasts." (PMID 26360410, 2015). "shRNA mediated PTPRZ1 down-regulation was used to study impact on tyrosine phosphorylation and in vivo tumor progression in SCLC cell lines." (PMID 23170925, 2012). "We found that PTPRZ1 has an important oncogenic role in tumor progression in the murine xenograft model of SCLCs." (PMID 23170925, 2012). "In another SCLC cell line, H1930, the reduction of PTPRZ1 expression decreased the rate of tumor formation under the skin in SCID mice as compared to the cells expressing the shLUC control." (PMID 23170925, 2012). "In non-tumor tissues, we specifically observed PTPRZ1 expression in the neural cells and endocrine cells such as peripheral nerves, pancreatic islets and adrenal chromaffin cells." (PMID 23170925, 2012). "To test this idea, we investigated the ability of PTPRZ1 to regulate tyrosine phosphorylation and tumor progression using SCLC cell lines." (PMID 23170925, 2012). "Note that PTPRZ1 was highly and specifically expressed in these tumor cells (left 2)." (PMID 40899632, 2025). "The attenuated knockout phenotype in H520 cells compared to HCC95 cells may be attributable to the closer resemblance of epigenetic modifications at the PTPRZ1 enhancer in HCC95 than H520 cells to those in tumor tissues." (PMID 40899632, 2025). "Of note, after initial tumor regression, some PTPRZ1-TCR-T-treated animals experienced tumor recurrence starting from day 42 onwards, yet by the predefined experimental endpoint, 33% (3 out of 9) of PTPRZ1-TCR-T cell-treated animals remained tumor-free, resulting in prolonged survival." (PMID 39893177, 2025). "We found that transferred human T cells in the tumor could only be detected in mice treated with PTPRZ1-TCR-T, even after 76 days following the last ACT." (PMID 39893177, 2025). "In addition, the single cell data also confirmed that PTPRZ1 was specifically expressed in the tumor‐like squamous cell cluster, in a patten similar to the 4 master TFs." (PMID 40899632, 2025). "Indeed, in the first five hours, PTPRZ11814-1822 TCR-T cells preferentially killed SCCs while after 24 h, both SCCs and FCCs were lysed, suggesting a preferential anti-tumor activity on stem-like SCCs by PTPRZ1-TCR-T." (PMID 39893177, 2025). "Furthermore, blocking the PTN–PTPRZ1 signaling using shRNA or an anti-PTPRZ1 antibody significantly suppressed GBM tumor growth and prolonged animal survival." (PMID 38732975, 2024).
tumor (continued). "Besides, PTPRZ1+ tumor cells display a high rate of tumorigenesis compared with matched PTPRZ1- in animal models." (PMID 38167429, 2024). "Since PTPRZ1 is part of the pseudohypoxia signature regulated by integrin α6β4, these observations suggest that integrin α6β4, through its sensing of the tumor microenvironment, could regulate pseudohypoxia to promote tumor progression." (PMID 39518121, 2024). "However, in a subsequent study, PTPRZ1 protein was detected in the tumor cells, was elevated in astrocytic gliomas of different malignancy grades, and was associated with an increasing malignancy grade." (PMID 37175798, 2023). "On the other hand, low PTPRZ1 expression seems to be related to a worse prognosis in some cancer types, suggesting that in some cases, it may act as a tumor-suppressor gene." (PMID 37175798, 2023). "These discrepancies may be due to our limited understanding of PTPRZ1 signaling and tumor microenvironments." (PMID 37175798, 2023). "A tumor atlas of primary GBMs created by a single-cell RNA-sequencing approach identified the outer radial glia-like cells, a cell-type population that undergoes a characteristic PTPRZ1-mediated mitotic translocation that promotes an invasive behavior." (PMID 37175798, 2023). "Interestingly, there was visually apparent co-localization of tumor neuroectoderm-like cells with high PTPRZ1, PTN, and FGFR3, identified as important for neuroectoderm-like neoplastic cell signaling as above." (PMID 36966348, 2023). "Moreover, Interference of PTN–PTPRZ1 signaling by shRNA or anti-PTPRZ1 antibody potently suppressed GBM tumor growth and prolonged animal survival." (PMID 35600367, 2022). "We then identified 4924 tumor cells (63.7% of the total cell population), characterized by a chromosome 7 gain and chromosome 10 loss, via inference of single-cell CNV state 5,10,11 and gene expression markers SOX2, PTPRZ1, and EGFR." (PMID 35941215, 2022). "Additionally, they showed that in vitro knockdown of PTPRZ1 in dissociated primary tumor samples and PDX lines attenuates invasion." (PMID 33613198, 2021). "The tumor tissues displayed an enriched expression of transcription factors (e.g., Dlx2, Gbx2, Foxb1, and Nkx2.2) critical for brain development, tanycyte markers (e.g., Ptprz1, Fabp7, Crym, and Gja1), and differentiation markers (e.g., Dcx, Olig1, and Cspg5)." (PMID 33863883, 2021). "As a marker of neuroglial origin, PTPRZ1 may add a bridge between the neurotransmitters, neurodevelopment, and tumor microtubes." (PMID 33317554, 2020). "PTPRZ1 was expressed with high intensity in most of the tumor samples, suggesting that it could be a good marker in NB." (PMID 31837707, 2019). "CSF-1, CSF-1R, and IL-34 were weakly negatively associated with tumor purity, while the lack of association between immune cell infiltration and gene expression of PTPRZ1 and syndecan-1 was also reflected by tumor purity values." (PMID 29796177, 2018). "Furthermore, CSF-1/CSF-1R also showed a higher correlation with tumor infiltrating lymphocytes (TILs) than IL-34, PTPRZ1, and syndecan-1." (PMID 29796177, 2018). "Moreover, mice bearing PTPRZ1+ cell-derived tumours displayed much more rapid tumour growth than mice implanted with PTPRZ1− cells (P<0.05, Student's t-test)." (PMID 28569747, 2017). "Importantly, bioluminescent analyses showed that PTPRZ1 disruption potently inhibited GSC tumour growth." (PMID 28569747, 2017). "Consequently, mice bearing the PTPRZ1+ xenografts exhibited markedly shortened survivals relative to those bearing the PTPRZ1− tumours." (PMID 28569747, 2017). "Moreover, blocking the PTN–PTPRZ1 signalling by shRNA or anti-PTPRZ1 antibody potently suppressed GBM tumour growth and prolonged animal survival." (PMID 28569747, 2017).